NANOGP4 (Nanog homeobox pseudogene 4)
Synonyms: NANOGP2
Gene: Transcribed processed pseudogene on chromosome 7 (29,212,302 to 29,213,214, forward strand). Ensembl gene ENSG00000237065.
Diseases named in the same sentence as NANOGP4 in open-access papers:
NANOGP4 is named in the same sentence as 1 disease in open-access papers, as found by Europe PMC text mining. Sharing a sentence is not in itself a finding about the gene and the disease. The quoted sentences say what the papers report.
cancer (1 paper, 2020). A tumor composed of atypical neoplastic, often pleomorphic cells that invade other tissues. "NANOG (NANOG1) has 11 pseudogenes, among which NANOGP4, P5, and P8 are expressed in cancer cells." (PMID 32197405, 2020).